CRP (C-reactive protein)
Diseases named in the same sentence as CRP in open-access papers (continued):
Sharing a sentence is not in itself a finding about the gene and the disease.
COVID-19 (continued). "At early post-acute COVID-19 follow-up, a substantial portion of study participants presented with low-grade thrombo-inflammation, as reflected by increased IL6, neopterin, pro-calcitonin, C-reactive protein (CRP) or d-dimer blood concentrations." (PMID 35736479, 2022). "Finally, a predictive nomogram model for the occurrence of AKI in hospitalized COVID-19 patients based on CAD, SaO2, PCT, CRP, and GFR was constructed." (PMID 36505004, 2022). "CRP and TXA2 serum levels and NF-κB p50, and NF-κB p65 mRNA expression revealed a significant positive connection with all other parameters in the severe COVID-19 patient group." (PMID 36298501, 2022). "CRP, a prominent marker of systemic inflammation, was elevated in the majority of COVID-19 patients with severe illness compared with mild or nonsevere patients." (PMID 36248417, 2022). "Among COVID-19 patients without comorbid conditions, sodium, potassium, CRP, ferritin, total protein, and albumin showed significant changes." (PMID 35165642, 2022). "In addition, albumin-based scores such as the CRP-to-albumin ratio (CAR) and PNI were also good predictors of COVID-19 disease severity." (PMID 36296963, 2022). "Upon admission, D-dimer levels, but not C-reactive protein, were significantly higher in COVID-19 patients taking ASA than in those without ASA." (PMID 36422187, 2022). "All inflammatory biomarkers in COVID-19 patients were significantly higher in hospitalised patients than in non-hospitalised patients, e.g., CRP 59.3 mg/l (IQR 31.5–126.9) vs. 2.3 mg/l (IQR 0.9–11.1), p<0.001." (PMID 35622838, 2022). "We observed higher CRP, C5a and sC5b-9 levels on admission in COVID-19 males compared to females, which was not evident in the control population." (PMID 36203596, 2022). "Galectin-3 levels discriminated well between severe and non-severe outcomes and correlated with markers of COVID-19 severity, (CRP, NLR, D-dimer, and neutrophil count)." (PMID 35115644, 2022). "Age, sex, NLR, and CRP levels alone, measured at hospital admission, were not good predictors of a poor prognosis in patients with moderate COVID-19." (PMID 35310845, 2022). "COVID-19 patients that needed hospitalization or intensive care unit (ICU) presented with pneumonia with fever, lymphopenia, highly elevated pro-inflammatory cytokines, C-reactive protein (CRP), serum ferritin, and D-dimers." (PMID 35205046, 2022). "Conversely, age, sex, comorbidity, neutrophil/lymphocyte ratio, CD8 T cell count, and c-reactive protein, fibrinogen, and D-dimer levels alone at admission were not good predictors of poor prognosis in patients with mild or moderate COVID-19." (PMID 35310845, 2022). "Furthermore, some inflammatory markers [i.e., C-reactive protein (CRP), interleukin-6 (IL-6), and ferritin] were reported as solid predictors of worse outcomes in COVID-19 positive patients." (PMID 35056135, 2022). "There is a strong inverse correlation between vitamin D level and the cytokine storm inflammatory markers like ferritin, D-dimer, CRP, LDH, and neutrophil to lymphocyte ratio especially in the fifth and tenth days of the ICU course of patients affected by COVID-19." (PMID 35221663, 2022). "In agreement with the literature, COVID-19-positive patients presented higher CRP levels compared with the COVID-19-negative group, with the highest levels reached in severely affected patients." (PMID 36555872, 2022). "The median level of C-reactive protein was significantly higher in children with MIS-C; however, the proportion of patients with elevated C-reactive protein was not significantly different between children with MIS-C and with acute COVID-19." (PMID 35428202, 2022). "A few days after receiving the COVID-19 mRNA vaccine, four people developed myocarditis, which was characterized by chest pain, increased troponin I and C-reactive protein, and negative viral serologies." (PMID 35974860, 2022).
COVID-19 (continued). "A further indication of the present study regards the NPV scores corroborating that early normal range blood parameters (AST, ALT, MGB, CK, CRP, Ferritin for women, LDH) in COVID-19 patients could lead to mild or light consequences." (PMID 35054342, 2022). "Three studies reported the level of C-reactive protein (CRP), with 158 patients in the COVID-19 positive group and 302 in the COVID-19 negative group." (PMID 36338951, 2022). "Clinical studies have shown that COVID-19 patients have higher serum level of cytokines (including TNF-α, IFN-γ, IL-6) and C-reactive protein (CRP), which may account for these patients' severe symptoms and a higher case fatality rate." (PMID 35733229, 2022). "We evaluated the role of CRP and other laboratory parameters in predicting the worsening of clinical conditions during hospitalization, ICU admission, and fatal outcome among patients with COVID-19." (PMID 36560453, 2022). "In addition, ANC, D-dimer at admission, CRP, and BUN can be used as independent predictors of in-patient mortality in COVID-19 patients in hospital settings." (PMID 35464560, 2022). "A significant positive correlation was observed between CRP and mRNA expression of TLR3 (rho = 0.85, P = 0.001), TLR7 (rho = 0.80, P = 0.004), TLR8 (rho = 0.78, P = 0.010), and TLR9 (rho = 0.48, P = 0.035) in the all COVID-19 cases." (PMID 35538443, 2022). "This may suggest that CRP and PCT may be used in the detection of newly emerging bacterial infections in pediatric COVID-19 patients." (PMID 35703526, 2022). "Indeed, both the Gale and Venturini COVID-19 severity scores have been included in clinical parameters and laboratory findings that could frequently be abnormal in infants with respiratory tract infection, even when not severe (such as tachypnea, poor feeding, leukopenia, elevated CRP)." (PMID 36298812, 2022). "In particular, IL-6 ≥ 74.98 pg/mL, CRP ≥ 81 mg/L, PCT ≥ 0.56 ng/mL, and D-dimer ≥ 760 ng/mL on admission to the ICU could effectively predict in-hospital mortality in COVID-19 patients." (PMID 35237386, 2022). "In subjects with an elevated plasma concentration of CRP but without COVID-19, no increase in FVIIa-AT was observed." (PMID 36428852, 2022). "In summary, this study showed that certain markers such as D-dimer, neutrophils, lymphocytes, CRP, LDH, ALT, and AST could predict ICU admission of the COVID-19 patients." (PMID 35510030, 2022). "More importantly, colorectal cancer patients with SARS-CoV-2 infection exhibited higher rates of lymphopenia, higher levels of hypersensitive C-reactive protein and a higher death rate than COVID-19 patients without colorectal cancer." (PMID 35017320, 2022). "We also found lower levels of CRP and PCT in the COVID-19 group." (PMID 35346080, 2022). "The COVID-19 Cardiac Score was trained to distinguish patients who recovered from those who died from complications, resulting in a model with the following predictors: age, sex, PCT, MYO, CRP, and cTnI." (PMID 36080827, 2022). "We aim to investigate the diagnostic accuracy and prognostic utility of the inflammatory biomarkers (IL-6, CRP, PCT, ferritin, and leukocytes) to predict hospitalisation and outcome in cases with COVID-19 and compare them with cases with respiratory infections other than COVID-19." (PMID 35622838, 2022). "Third, our results showed that non-severe patients with COVID-19 who had a level of hs-cTnI ≥ 5 ng/L had significantly higher levels of CRP and lung involvement and lower levels of SpO2 and lymphocyte count compared with those with hs-cTnI under 5 ng/L." (PMID 35149778, 2022). "Kaplan–Meier survival curves with logarithmic rank tests were constructed to compare the cumulative incidence of death from coagulation abnormalities, positivity for CRP and calcium ESR, levels among 45 patients with COVID-19, and the presence of diabetes among patients." (PMID 36570594, 2022).
COVID-19 (continued). "Raised CRP is part of a highly inflammatory environment in COVID-19 with prolonged high viral load due to the lack of a strong type I IFN response." (PMID 36685582, 2022). "It has already been established that laboratory tests better predict the severity of COVID-19 infection, with biomarkers such as D-Dimer, CRP and LDH considered as the most important in the initial screening of patients infected with COVID-19 when they visit a hospital." (PMID 36292474, 2022). "CRP, described in the literature as a good biomarker in COVID-19 patients, was not suitable to identify the Long-COVID syndrome." (PMID 36211365, 2022). "The immunological feature of severe COVID-19 could be defined by the “core signature” cytokines in cluster 2: MCP-3, IL-6, IFN-γ, and CXCL10, which strongly correlated with each other and CRP, and are involved in cytokine release storm." (PMID 35350784, 2022). "The existing body of research on COVID-19 has demonstrated the use of inflammatory markers, including serum amyloid A (SAA), C-reactive protein (CRP), white blood cell (WBC) counts, lymphocyte and platelet counts, and erythrocyte sedimentation rates as inflammatory indicators." (PMID 36465717, 2022). "Serum ESR (p = 0.0013), CRP (p = 0.0067), LDH (p = 0.0004) and CPK (p = 0.0077) levels were higher in severe COVID-19 patients at baseline than in mild patients whilst baseline levels of all but CPK (p = 0.1193) were also higher in moderate patients compared with mild patients." (PMID 35187271, 2022). "From a clinical point of view, it should be noted that, in the present paper, CRP levels were within normal range among COVID-19 patients as well, again as opposed to studies of patients with severe disease." (PMID 35222429, 2022). "The situation was studied, and our findings suggest that for COVID-19-affected patients undergoing chemotherapy for lung cancer, a history of ICI within 90 days and elevated CRP level (≥ 2.75 mg/dL) were found to be potential factors leading to respiratory failure." (PMID 36316726, 2022). "In patients with mild COVID-19, a negative correlation of C-reactive protein (CRP) with C. butyricum was observed." (PMID 35336884, 2022). "Using pGSN, CRP, IgG, IgM or IgA alone were not significantly predictive, however the AUCs of pGSN/IgG and pGSN/IgM to predict severe COVID-19 were 0.893 (p=0.028) and 0.96 (p=0.01) respectively (Supplementary S4A)." (PMID 36148234, 2022). "A significant elevation of CRP in COVID-19 non-survivors would come as no surprise as hyperinflammation is the key pathology in severe cases of COVID-19." (PMID 35464560, 2022). "A surge in serum levels of CRP is a consistent finding in infectious pathology, with COVID-19 as no exception." (PMID 35888173, 2022). "Accordingly, the effects of gender, age, DM, and HT on the salivary levels of IL-6, CRP, and CXCL-10 observed in SARS-CoV-2 patients might be consequences of their impacts on COVID-19 disease severity." (PMID 35967091, 2022). "In addition to clinical ones, laboratory evidence must be presented, and it includes elevation of at least two inflammatory markers (CRP, procalcitonin, ESR, ferritin, IL6), and positive COVID-19 PCR or serology tests." (PMID 35494997, 2022). "However, a direct correlation between CRP and LDH levels in COVID-19 patients and the worsening of the respiratory function has not been proven yet." (PMID 36560453, 2022). "A previous meta-analysis showed that elevated CRP, D-dimer, and LDH could predict the high severity of COVID-19." (PMID 35510030, 2022). "Other outcome measures were the increase in C-reactive protein (CRP) levels, ARDS development, COVID-19 severity, length of stay (LOS) of SARS-CoV-2-infected patients and a composite outcome including ICU referral and ICU LOS, need for endotracheal intubation, and mortality." (PMID 35807167, 2022).
COVID-19 (continued). "Regarding the hyperinflammation, we observed BK1-8 was positively and significantly related to four out of five inflammation markers studied (CRP, ferritin, IL-1β, IL-6, and TNF-α), suggesting a potential role of this peptide in patients with COVID-19’ inflammation." (PMID 35812405, 2022). "The abnormality in blood cell counts and coagulation factors suggested viral/bacterial (co)infection and the induced inflammatory response, further confirmed by the heightened levels of c-reactive protein (CRP) and procalcitonin (PCT) in most patients of COVID-19 and influenza cohorts." (PMID 36062112, 2022). "Statin users showed a lower mean of white blood cell count (7.6 × 103/μL vs. 8.1 × 103/μL, p < 0.01), and C-reactive protein (100 mg/L vs. 120.7 mg/L, p < 0.001) compared to non-statin COVID-19 patients." (PMID 35865966, 2022). "In addition, the creation of IL-1β drives the synthesis of IL-6, a cytokine that induces C-reactive protein (CRP) and which has been identified as a major pro-inflammatory agent in the COVID-19 cytokine storm." (PMID 35163769, 2022). "There were some signals that survivors with PCS had a more severe course of disease (CRP at admission, severity of COVID-19, length of hospital stay) than survivors without PCS." (PMID 35217881, 2022). "Inflammatory parameters (IL-6, CRP; IL-6/Ly ratio) are significantly elevated in non-survivor critically-ill patients with COVID-19." (PMID 36142336, 2022). "In the patients who were admitted to C1, mean CRP levels were significantly higher in COVID-19 patients with pneumonia when compared with COVID-19 patients without pneumonia (3.0543 ± 4.379 vs 0.9103 ± 1.662, p = 0.001)." (PMID 34493032, 2022). "At the time of SARS-CoV2 diagnosis, COVID-19 non-survivors had significantly higher CRP, IL-6, D-Dimer, and antithrombin levels compared to the survivors." (PMID 35883726, 2022). "The main finding in the present study was that hospitalized COVID-19 patients have a worse prognosis with lower SA values and higher CRP values at admission, irrespective of other confounding variables." (PMID 35740416, 2022). "For example, in critical patients with COVID-19, a negative correlation was observed between serum C-reactive protein (CRP) levels and the gut abundance of C. butyricum and F. prausnitzii." (PMID 35391730, 2022). "Indeed, serum levels of inflammatory mediators and markers, including interleukin (IL)-6, C-reactive protein (CRP), IL-1β, IL-10, CXCL9, CXCL10, ferritin, and tumor necrosis factor-α (TNF-α) are elevated in cases of COVID-19." (PMID 35053424, 2022). "Likewise, patients with SARS-CoV-2 and DM have increased levels of IL-6 and C-reactive protein (CRP), which can favour the systemic inflammatory response accompanying the typical acute respiratory distress syndrome in COVID-19." (PMID 35956122, 2022). "We also assessed whether the 6-mRNA score is an independent predictor of severity in patients with COVID-19 by including other predictors of severity (age, SOFA score, CRP, PCT, lactate, and gender) in a logistic regression model." (PMID 35042868, 2022). "Of note, in this study, IL-6 level in saliva of COVID-19 was positively associated with ferritin and had a positive trend with other markers of COVID19 severity, D-Dimer and CRP, although not to a significant level (P = 0.1)." (PMID 36163397, 2022). "Although CRP is inadequate indicator for treatment of COVID-19 because CRP production by IL-6 pathway is suppressed by TCZ, LDH, which indicates lung injury and severity of COVID-19, also showed a decreasing trend." (PMID 34436742, 2022). "In the multivariate Cox regression analysis model, remdesivir use remained protective of worse survival independently of older age, higher comorbidity burden, critical severity of COVID-19 on admission, higher WBC, higher CRP, and start of remdesivir treatment during lower oxygen requirement." (PMID 36597565, 2022).
COVID-19 (continued). "The majority of studies have shown that LA is known to prolong PTT and is detected in a significant proportion of COVID-19 infected patients, resulting in increased fibrinogen and factor VIII levels, elevated levels of biomarkers such as CRP, and the presence of aPLs, which can affect PTT." (PMID 36570594, 2022). "The present study shows that some differences were found between COVID-19-positive patients with proximal femoral fractures in Italy and Iran in terms of mean age, length of hospital stay, number of transfusions, WBC count and CRP values." (PMID 35744044, 2022). "COVID-19; SARS-CoV-2; Neopterin; CRP; IL-6; Viral infection; Biomarker." (PMID 35529699, 2022). "The CRP, WBC, and LDH levels of the discharged COVID-19 patients decreased over time." (PMID 36060378, 2022). "COVID-19, in the absence of bacterial or fungal infection, causes elevations in white blood cell count (WBC), C-reactive protein (CRP), and sedimentation rate (ESR)." (PMID 36102000, 2022). "Our findings positioned CA125 as an independent biomarker of fatal outcomes in patients hospitalized for COVID-19, above the classical inflammation markers described in the literature (ferritin, procalcitonin, LDH, and C-reactive protein) or biomarkers of myocardial damage (T troponin and pro-BNP)." (PMID 36337886, 2022). "This study demonstrated that increased CRP and LDH were risk factors for severe events in all enrolled COVID-19 patients, but cancer as a chronic disease was not a risk factor for severe events in COVID-19 patients." (PMID 36033814, 2022). "We also observed higher levels of C-reactive protein and neutrophil counts in non-survivor vs survivor COVID-19 infected cancer patients with diabetes." (PMID 36059615, 2022). "In contrast to our model, the 4 C includes some laboratory values (urea level and C-reactive protein) not always available in ED, and used data from COVID-19 positive patients admitted to the hospital: AUROC 0.79, (95% CI 0.78–0.79)." (PMID 34986168, 2022). "In contrast, our patients with severe COVID-19 presented early in the course of illness (median 3 days after symptom onset), had no lymphopenia (median absolute lymphocyte count, ALC 4.1 x 109/L) and normal CRP levels (median CRP 1.6 mg/L)." (PMID 35547549, 2022). "Since biomarkers of treatment response in COVID-19 are lacking, to our knowledge, this result is novel, supporting the use of CRP measurement during the disease course to guide patient management." (PMID 35242241, 2022). "At clinical level, quercetin has shown positive effects in the treatment of COVID-19 patients by decreasing the serum levels of alkaline phosphatase (ALP), quantitative C-reactive protein (q-CRP), and lactate dehydrogenase (LDH), as critical markers involved in COVID-19 severity." (PMID 35694174, 2022). "Added to combining selective recognized biochemical markers of COVID-19 severity (ANC, CRP, LDH, BUN and ferritin), the triad of elevated serum IL-10, PD-L1 and TNF-α improved the current model accuracy to predict the severity of the disease, through the stepwise linear regression model." (PMID 35529862, 2022). "Among elevated plasma inflammatory mediator levels; CRP, ICAM-1, SAA, VCAM-1, CXCL10, IL-7, IL-10 and Flt-1 may suggest the severity of COVID-19." (PMID 35958594, 2022). "Taken together, the use of the combination of SAA and CRP levels, along with WBC, lymphocyte, and neutrophil counts, greatly increased the sensitivity and specificity of disease severity and mortality prediction for COVID-19 in the present study." (PMID 36465717, 2022). "However, COVID-19-related ARDS is inherently an inflammatory lung disease, and the importance of CRP was ranked highest across all models." (PMID 36437469, 2022). "The NP levels were significantly higher in the COVID-19 patients than in the non-COVID-19 patients, while biopterin, CRP and IL-6 were not changed significantly." (PMID 35529699, 2022).